RNU6-346P (RNA, U6 small nuclear 346, pseudogene)
Gene: Small nuclear RNA gene on chromosome 18 (76,800,664 to 76,800,774, reverse strand). Ensembl gene ENSG00000252097.
Homologues: Orthologues: macaque U6 (76% identical), dog U6 (50% identical), rat LOC120101972 (50% identical), mouse Gm24552 (44% identical), zebrafish U6 (39% identical). Paralogues in human: RNU6-1249P (60% identical), RNU6-716P (59% identical), RNU6-132P (59% identical), RNU6-744P (59% identical), RNU6-1062P (58% identical), RNU6-1201P (58% identical), RNU6-153P (58% identical), RNU6-21P (58% identical), RNU6-234P (58% identical), RNU6-463P (58% identical), RNU6-643P (58% identical), RNU6-899P (58% identical), and 1281 more.